PAX6 (paired box 6)
Diseases named in the same sentence as PAX6 in open-access papers (continued):
Sharing a sentence is not in itself a finding about the gene and the disease.
retinoblastoma (continued). "And the suppression of PAX6 mRNA expression resulted in an inhibited growth and an increased apoptosis of cultured human retinoblastoma cells." (PMID 24454925, 2014). "In conclusion, our data demonstrate that the suppression of PAX6 increases proliferation and decreases apoptosis in human retinoblastoma cells by regulating several cell cycle and apoptosis biomarkers." (PMID 24939714, 2014). "The expression of endogenous PAX6 was knocked down using PAX6-specific lentivirus in two human retinoblastoma cell lines, SO-Rb50 and Y79." (PMID 24939714, 2014). "In this study, we found that inhibition of PAX6 in human retinoblastoma cell lines led to a low apoptotic rate which was supported by the changes in the levels of apoptosis-related proteins (Bcl-2 and BAX)." (PMID 24939714, 2014). "Using a lentiviral vector-mediated transfection of human retinoblastoma cells, our study demonstrates that the inhibition of endogenous PAX6 expression results in decreased retinoblastoma cell apoptosis in vitro." (PMID 24939714, 2014). "The aim of this study was to investigate the role of the transcription factor, PAX6, in the development of retinoblastoma." (PMID 24939714, 2014). "Overexpression of Pax6 can change development and function in some cells, and the level of Pax6 directly maintains normal corneal epithelial cells, but inhibits the growth of cultured human retinoblastoma cells." (PMID 22065923, 2011). "In conclusion, retinoblastoma development is regulated by the ZFPM2-AS1/511-3p/PAX6 axis." (PMID 34989314, 2022). "EZF1-AS1 promoted retinoblastoma cell viability and suppressed apoptosis via PAX6." (PMID 33432525, 2021). "We then measured the effect of FEZF1-AS1 on retinoblastoma cell viability and apoptosis by PAX6." (PMID 33432525, 2021). "The data indicated that FEZF1-AS1 affected miR-363-3p/PAX6 expression in retinoblastoma cells." (PMID 33432525, 2021). "In addition, the pRB (Retinoblastoma) S780 phosphorylation level is decreased in lung cancer PAX6 KD cells." (PMID 29716531, 2018). "It is possible that among the retinal cell types that fail to develop due to loss of Pax6 is the retinoblastoma cell of origin and therefore, no tumors are formed." (PMID 25338120, 2014). "To determine whether Pax6 upregulation in the 7D retina has an effect in retinoblastoma tumorigenesis, we generated Chx10-Cre;RbLox/Lox; −107−/−;;Pax6Lox/Lox (Pax6 TKO) mice and aged them for 400 days." (PMID 25338120, 2014). "PAX6 is frequently expressed in retinoblastoma, pancreatic tumors, and intestinal tumors." (PMID 24454925, 2014). "Therefore, in the present study, we suppressed the expression of Pax6 in human retinoblastoma cells and examined the effects on cell growth and apoptosis." (PMID 24939714, 2014). "The different response to CN-A on PAX6 transcription in two retinoblastoma cell lines is unique." (PMID 20577596, 2010). "To confirm whether CN-A activates the PAX6 promoter, we investigated the luciferase activity of the promoters in two retinoblastoma cell lines after 48 h treatment with 10 μg/ml CN-A." (PMID 20577596, 2010). "Notably, PAX6 was found to regulate the cell growth in retinoblastoma." (PMID 33432525, 2021). "However the physiological role of PAX6 in retinal development and the oncogenesis in retinoblastoma remains largely unknown." (PMID 24939714, 2014). "We speculate that among the retinal cell types that fail to develop due to loss of Pax6 is the retinoblastoma cell of origin and therefore, no tumors are formed." (PMID 25338120, 2014). "Moreover, we demonstrated that inhibiting miR-511-3p reversed the negative effects of silencing ZFPM2-AS1 and PAX6 on retinoblastoma cell viability and migration." (PMID 34989314, 2022). "Furthermore, miR-433 inhibits retinoblastoma by suppressing the expression levels of notch homolog 1 (Notch1) and paired box protein Pax-6 (PAX6)." (PMID 28402262, 2017).
retinoblastoma (continued). "In both retinoblastoma cell lines, the levels of Bcl-2, CDK1 and PCNA were significantly upregulated in the PAX6 inhibition study groups than in negative GFP-control groups (Bcl-2, t=−5.90, P<0.05 and t=−4.86, P<0.05, resp." (PMID 24939714, 2014).
Wilms tumor (24 papers, 2009 to 2025). An embryonal neoplasm characterized by the presence of epithelial, mesenchymal, and blastema components. "Additionally, Pax6 has been linked with WAGR (Wilm’s tumor, Aniridia, Genitourinary malformations, and mental Retardation syndrome) which is co-morbid for ASD." (PMID 35942939, 2022). "Following detailed mapping of this chromosome region, the causative genes for Wilms tumour and genitourinary anomalies (WT1) and classical aniridia (PAX6) were found to lie within a megabase of each other." (PMID 30242502, 2019). "Some sporadic cases have a risk of developing Wilms tumor as a part of WAGR (Wilms tumor, aniridia, genitourinary abnormalities, and mental retardation; OMIM 194072), which is caused by deletion of both PAX6 and Wilms’ tumor gene (WT1) in the 11p13 region." (PMID 22393275, 2012). "The syndrome is caused by haploinsufficiency for the PAX6 gene (causing aniridia) and the WT1 gene (predisposing Wilms' tumor, genital abnormalities and nephropathies)." (PMID 19222835, 2009). "Furthermore, the homologs of these genes near pax6 were located in the WAGR (Wilms tumor, Aniridia, genitourinary abnormalities, and mental retardation) region of human." (PMID 30959850, 2019). "Most obviously, individuals who have deletions encompassing both PAX6 and WT1 should be screened for Wilms tumour as earlier detection almost certainly improves outcome." (PMID 30242502, 2019).
autism (23 papers, 2008 to 2025). Persistent deficits in social interaction and communication and interaction as well as a markedly restricted repertoire of activity and interest as well as repetitive patterns of behavior. "The presence of autism-related genes was evaluated, given the association of Pax6 mutations with ASD and the observation of social behavioral deficits in Pax6Sey/+ mice." (PMID 39902612, 2025). "There are case reports showing psychiatric and cognitive disorders such as mental retardation, autism, auditory ineterhemispheric transfer deficits, auditory and verbal working memory deficits, and frontal lobe dysfunction in patients with PAX6 mutations." (PMID 27355350, 2016). "Neurological disorders such as mental retardation, autism, epilepsy, cognitive impairments or behavioral abnormalities are uncommon in individuals with PAX6 mutations." (PMID 25628759, 2015). "These accumulating lines of evidence suggest that PAX6 mutations display concomitant phenotypes of autism." (PMID 21203536, 2010). "They stated that autism, in their case, may be caused by a combination of the PAX6 enhancer deletion and deletion of the other genes in the deleted region." (PMID 24349436, 2013). "Furthermore, chromosome 11p13, on which PAX6 is located, is implicated as a possible locus for autism susceptibility by a linkage study." (PMID 21203536, 2010). "In addition, 11p12-13 locus covering PAX6 gene is suggested as one of the autism linkage loci, and we have previously reported a mutation in PAX6 found in a autistic patient." (PMID 21203536, 2010). "We observe a considerable overlap with autism-associated genes and suggest that studying Pax6-dependent gene regulatory networks may further our insight into molecular mechanisms implicated in autistic-like behaviors in Pax6 mutations, thereby paving the way for future research in this area." (PMID 39902612, 2025). "However, PAX6 itself should also be considered, since some patients with PAX6 intragenic mutations present with cerebral abnormalities as well as development delays and autism." (PMID 31861090, 2019). "Among these, three (PAX6, TCF4, and ZMIZ1) are ASD risk genes according to the Simons Foundation Autism Research Initiative (SFARI) gene database." (PMID 35942939, 2022). "Assessment of cell identity acquisition in autism-iPSCs showed that PAX6 dCTA was 317 cells/day and Tuj1 dCTA was 368 cells/day." (PMID 32826066, 2021). "In contrast in the autism group, expression of PAX6 and Tuj1 at day 9 was lower than in the control group." (PMID 32826066, 2021). "Future analyses of behavior in Pax6 female mutant rats/mice would be interesting in light of the more severe symptoms often observed in female subjects with autism." (PMID 27355350, 2016). "One patient had an intact PAX6 gene, however, ophthalmologic findings of the patient were not described since the scope of the paper was the mental retardation and autism observed in WAGR patients." (PMID 19222835, 2009). "An apparent deletion of a single probe in PAX6 was observed in an affected boy, and in his affected brother and sister (all with a diagnosis of autism)." (PMID 18925931, 2008). "First, we assessed the expression of PAX6 and Tuj1 in control- and autism-iPSCs." (PMID 32826066, 2021). "Furthermore, the radial organisation of Pax6-positive NPCs around ZO-1-positive lumens was disrupted in autism hCSs compared to control hCSs." (PMID 33482917, 2021). "This may explain the high rate of PAX6+ and Tuj1+ precursor generation between days 9 and 21 in autism-iPSCs." (PMID 32826066, 2021). "However, despite this increased rate of cell identity acquisition, PAX6 and Tuj1 expression was still significantly lower at day 21 in autism-iPSCs than in control-iPSCs." (PMID 32826066, 2021).
autism (continued). "Reduction in exploratory behaviour in adulthood was documented in other animal models of autism – Pax6 heterozygous mutant (rSey2/+) rats with alterations in serotonergic system, mice with disruption in chromosome 7 (analogue of human locus 15q11-13), BALB/cByJ mice." (PMID 24678262, 2013). "Thus, it is possible that deregulation of GAA, KIF1B and SNCA is involved in pathology of human PAX6 patients with a range of neurological disorders including autism, cognitive disorders, epilepsy and mental retardation." (PMID 23342162, 2013). "In this study, we examined whether and/or how much Pax6 heterozygous rats model autism." (PMID 21203536, 2010).
glioma (23 papers, 2010 to 2025). A benign or malignant brain and spinal cord tumor that arises from glial cells (astrocytes, oligodendrocytes, ependymal cells). "Interestingly, PAX6 has been implicated as a cell cycle regulator by arresting cells in the G0/G1‐phase in human gliomas." (PMID 34459131, 2021). "In gliomas, higher levels of PAX6 mRNA were associated with better survival." (PMID 29568088, 2018). "In glioblastoma, PAX6 expression is associated with glioma grade." (PMID 29716531, 2018). "Our previous research demonstrated that PAX6 is regulated by microRNA-223, and the overexpression of PAX6 significantly inhibited glioma cell proliferation and invasion while increasing sensitivity to the chemotherapeutic agent temozolomide." (PMID 41154694, 2025). "Studies have shown that PAX6 expression is decreased in gliomas and is positively correlated with a glioma patient’s prognosis." (PMID 41154694, 2025). "Understanding how PAX6 operates specifically in gliomas is therefore essential for elucidating the molecular pathological basis of glioma development and developing targeted therapeutic strategies." (PMID 41154694, 2025). "Our findings highlight PAX6 as a pivotal regulator of ferroptosis, offering new insights into glioma pathophysiology and uncovering promising targets for therapeutic intervention." (PMID 41154694, 2025). "Western blot results on tumor tissues demonstrated that PAX6 overexpression can reduce the expression of the GPX4 protein in glioma cells, indicating the potential role of PAX6 in inducing ferroptosis in glioma cells." (PMID 41154694, 2025). "Immunohistochemical staining analysis of the excised tumor tissues revealed that PAX6 overexpression also markedly suppressed the expression of HIF-1α in glioma cells in vivo, consistent with the findings from in vitro experiments." (PMID 41154694, 2025). "In summary, this study illustrates that PAX6 promotes ferroptosis in glioma cells by suppressing HIF-1α by regulating intracellular ROS and oxidative stress." (PMID 41154694, 2025). "LPO levels were significantly elevated in both cell lines compared to the control (empty vector-transfected) cells, suggesting that PAX6 overexpression induces oxidative stress in glioma cells." (PMID 41154694, 2025). "While PAX6 is known to suppress glioma cell proliferation via mechanisms involving the Sonic hedgehog pathway, VEGF signaling, and the sphingosine kinase, its downstream molecular targets and regulatory network remain inadequately defined." (PMID 41154694, 2025). "This study reveals a novel tumor-suppressive mechanism of PAX6 in gliomas, whereby it inhibits HIF-1α to induce ferroptosis, ultimately suppressing tumor growth." (PMID 41154694, 2025). "We assessed PAX6 expression of tumor tissues from 98 glioma patients across pathological grades 1–4 and 11 brain tissue samples (gray matter tissues of the brain containing glial cells) by tissue microarray technology." (PMID 41154694, 2025). "Our research provides a reference basis for a deeper understanding of the role of PAX6 in ferroptosis of glioma." (PMID 41154694, 2025). "If further research is to be conducted on the potential therapeutic targets of PAX6 in gliomas, it is a very necessary step to verify its efficacy in clinical glioma patients." (PMID 41154694, 2025). "Our findings enhance the understanding of glioma pathogenesis and the role of PAX6, while also providing an experimental foundation for further investigating the PAX6/HIF-1α axis." (PMID 41154694, 2025). "PAX6 expression is significantly decreased in glioma, and the expression levels are closely related to glioma development and prognosis." (PMID 41154694, 2025). "Immunohistochemistry showed that PAX6 expression progressively decreased with increasing glioma grade." (PMID 41154694, 2025). "Previous studies indicate that overexpression of PAX6 markedly reduces the protein level of hypoxia inducible factor-1α (HIF-1α) in glioma cells." (PMID 41154694, 2025).
glioma (continued). "Firstly, immunohistochemistry, qPCR, Western blot, and other methods were used to detect PAX6 and HIF-1α expression in glioma tissues and cells, as well as the specific way in which PAX6 regulates HIF-1α." (PMID 41154694, 2025). "In this study, we found that PAX6 expression decreased with increasing glioma pathologic grade, supporting its role as a tumor suppressor." (PMID 41154694, 2025). "This study proposes that PAX6 induces (ROS) accumulation in glioma cells, which subsequently suppresses HIF-1α expression and promotes ferroptosis." (PMID 41154694, 2025). "It was found that overexpression of HIF-1α enhanced glioma cell proliferation and partially rescued the growth inhibition induced by PAX6." (PMID 41154694, 2025). "Paired box 6 (PAX6) is a DNA-binding transcription factor that downregulates the expression of the vascular endothelial growth factor A (VEGFA) gene in glioma cells to suppress tumor cell invasion." (PMID 35935861, 2022). "Actually, there are case reports showing downregulation of PAX6 in glioma samples (see reviews and the references therein)." (PMID 35682795, 2022). "PAX6, BCL6, HOXD13, and FOX2 have also been shown to be associated with glioma in previous studies 48-50." (PMID 33537074, 2021). "In both medulloblastoma and glioma cells, PAX6 expression is controlled by SHH-GLI signaling events: GLI1 activates PAX6 expression in medulloblastomas but suppresses it in gliomas." (PMID 34012965, 2021). "In glioma cells, PAX6 suppressed the expression of vascular endothelial growth factor A and the angiogenesis of glioma cells." (PMID 33182335, 2020). "The homeobox gene DLX5, Distal-Less Homeobox 5, has been shown to affect glioma cell motility via the PAX6/DLX5-WNT5A axis." (PMID 32513296, 2020). "In gliomas, PAX6 acts as a tumor suppressor reducing tumor growth, and PAX6 expression is reduced with the malignancy of glioma." (PMID 29716531, 2018). "Recently, PAX6(5a) was shown to play an important role in regulation of glioma progression by reducing cell survival and decreasing migration and invasion in glioblastoma cell lines." (PMID 29716531, 2018). "The concentration of 300 μM was chosen as Chang and colleges found that PAX6 increased glioma cell sensitivity to detachment induced oxidative stress at ROS levels comparable with what 300 μM H2O2 induce." (PMID 29716531, 2018). "PAX6 is also involved in inhibiting angiogenesis in gliomas, as it is found to downregulate expression of vascular endothelial growth factor A (VEGFA), the main angiogenic factor overexpressed in GBM." (PMID 29716531, 2018). "It has previously been shown that mir-335 affect the colony forming abilities of glioma cells, and that regulation of PAX6 expression contribute to this." (PMID 29716531, 2018). "Up-regulation of miR-335 in glioma cells reduces expression of PAX6, thus promoting cell proliferation and is accompanied by increased protein levels of MMP-2 and MMP-9." (PMID 26204513, 2015). "This study is a continuation of her study of PAX6 in glioma, focusing on identification of a therapeutic target/agent for GBM treatment." (PMID 21955618, 2011). "Via the MET tyrosine kinase receptor, Pax6 participates in cancer progression; some researchers have found that glioma angiogenesis can be restrained by Pax6." (PMID 22065923, 2011). "Tumor suppressor activity has been proposed for PAX6 in gliomas, in addition to its well‐known role in the eye development." (PMID 20500513, 2010). "Furthermore, overexpression of PAX6 can increase the concentration of Fe2+ within glioma cells, while overexpression of HIF-1α has the opposite effect." (PMID 41154694, 2025). "Previous studies have suggested that PAX6 also functions a tumor suppressor in gliomas." (PMID 41154694, 2025).